CSF1 (colony stimulating factor 1)
Diseases named in the same sentence as CSF1 in open-access papers (continued):
Sharing a sentence is not in itself a finding about the gene and the disease.
hepatocellular carcinoma (39 papers, 2007 to 2025). A malignant tumor that arises from hepatocytes. "For example, in hepatocellular carcinoma, the macrophage colony-stimulating factor (CSF-1) and its receptor regulate tumor-associated macrophages (TAMs)." (PMID 39757310, 2025). "Intriguingly, the expression levels of ASH1L, CCL2, and CSF1 further decreased in hepatoma cells if ASH1L was simultaneously knocked down in the cocultured HSCs, and vice versa (data not shown)." (PMID 39377228, 2024). "IL-1β produced by inflammatory macrophages increases PD-L1, as well as HIF-1α-dependent CSF-1 expression in hepatoma cells, facilitating TAM accumulation." (PMID 36845555, 2023). "CSF1 expression is significantly increased in hepatocellular carcinoma and is positively correlated with tumor severity." (PMID 37895197, 2023). "High expression of secreted OPN in hepatoma stimulates colony-stimulating factor 1 (CSF1)/CSF1R activation in macrophage which further increases PD-1 expression in hepatoma cells." (PMID 36906534, 2023). "Glutamate excretion by IL-1β-induced SLC7A11 overexpression can also promote hepatoma metastasis through the upregulation of programmed death ligand 1 (PD-L1) and colony-stimulating factor 1 (CSF1)." (PMID 36552652, 2022). "It has been revealed that TAMs secrete excess colony-stimulating factor-1 (CSF1) with the help of OPN in hepatocellular carcinoma TME." (PMID 35898884, 2022). "For example, CSF1 enhances the progression of hepatocellular carcinoma by inducing AIF1 expression in TAMs." (PMID 31629410, 2019). "Recent investigations into hepatocellular carcinoma have revealed that osteopontin (OPN) facilitates the M2-like polarization of macrophages and induces PD-L1 expression in hepatocellular carcinoma by activating the colony-stimulating factor-1 (CSF1)/CSF1 receptor (CSF1R) pathway." (PMID 38273373, 2024). "Therefore, this study analyzed the oncogenic and immunologic roles of SPP1 and CSF1 in hepatocellular carcinoma (HCC)." (PMID 37097499, 2023). "In hepatocellular carcinoma, this factor has been named colony-stimulating factor 1 (CSF1)." (PMID 33800554, 2021). "CSF‐1, CCL2, and IL‐15 are found to enhance the clearance of macrophages on hepatocellular carcinoma (HCC) cells." (PMID 41427020, 2025). "To further verify the interaction between SPP1 and CSF1, we analyzed the interaction between SPP1 and CSF1 in hepatoma cell lines." (PMID 37097499, 2023). "In hepatocellular carcinoma (HCC), tumor-released OPN can stimulate macrophages to secrete CSF1 through the PI3K–ATK–p65 signaling pathway and then induce infiltration of macrophages." (PMID 35898884, 2022). "In hepatocellular carcinoma (HCC), the OPN/CSF1/CSF1R axis plays a critical role in the immunosuppressive nature of the HCC microenvironment." (PMID 34423566, 2021). "Additionally, it has been reported that circASPA1 promoted hepatocellular carcinoma (HCC) progression by regulating miR-326/miR-532-5p-MAPK1 signaling, and positively correlated with tumor-associated-macrophage infiltration via the miR-326/miR-532-5p-CSF-1 axis." (PMID 33363156, 2020). "In hepatocellular carcinoma (HCC), CSF1/CSF1R blockade has been reported to serve a critical role in the immunosuppressive nature of TMEs." (PMID 32724427, 2020). "It has been shown that IL-1β-induced solute carrier family 7 member 11 (SLC7A11) overexpression upregulates PD-L1 and colony-stimulating factor 1 (CSF1) through the α-ketoglutarate/HIF1α axis, promoting MDSCs recruitment and infiltration in the hepatocellular carcinoma tumor niche." (PMID 38609997, 2024). "It has been reported that IL-1 β increased the level of SLC7A11, then up-regulated the expression of PD-L1 and CSF1 by regulating α-KG/HIF1 α and promoted the infiltration of tumor-related macrophages and myeloid suppressor cells to increase the metastasis of hepatocellular carcinoma." (PMID 38137387, 2023).
hepatocellular carcinoma (continued). "These functions were carried out by acting as a ceRNA for known tumor suppressors in hepatocellular carcinoma, i.e., miR-326 and miR-532-5p, and subsequently regulating MAPK1 (mitogen-activated protein kinase 1) and CSF-1 (colony-stimulating factor 1) pathways." (PMID 33717646, 2021). "In addition, osteopontin overexpression upregulates PD-L1 expression in hepatocellular carcinoma cells by activating the CSF1–CSF1R pathway in macrophages, and blockage of CSF1/CSF1R prevents TAM trafficking." (PMID 31474227, 2019). "In a study performed with a murine model of hepatocellular carcinoma, treatment with a CSF1R inhibitor resulted in increased CD8 infiltration accompanied by a reduction in MDSCs, a profile similar to what we observed in our study with the MC38 CSF1 knockout model." (PMID 37505292, 2023). "For example, circASAP is upregulated in hepatocellular carcinoma (HCC) and accelerates HCC cell metastasis by combining miR-326 and miR-532-5p, thereby regulating the expressions of MAPK1 and CSF-1." (PMID 35295711, 2022). "Recently, research has shown that miR-148b, which controls the expression of colony-stimulating factor 1 (CSF1), is downregulated in metastatic hepatocellular carcinoma cells (HCC)." (PMID 34680611, 2021).
Arthritis (37 papers, 2010 to 2025). Inflammation of a joint. "Our analyses further suggest that CSF1 positively regulates pathogenic macrophages and monocytes in these murine models of arthritis." (PMID 31552020, 2019). "With regard to experimental arthritis, it is interesting to note that the lack/blockade of CSF-1 as well as the blockade of CSF-1R is associated with less severe methylated bovine serum albumin (mBSA)-induced arthritis and CIA." (PMID 30886947, 2017). "Taken together, these data suggest that baricitinib greatly suppressed arthritis-induced inflammatory and neuropathic pain through the inhibition of IL-6 Amp and the subsequent decrease in Csf1 expression in DRG." (PMID 38879555, 2024). "In experimental and clinical arthritis, TREM-1 is well known to mediate the release of proinflammatory cytokines and chemokines, including CSF-1, that are all implicated in RA disease pathogenesis." (PMID 36012120, 2022). "Blockade of CSF1 alone or of both CSF1/IL34 for 9 weeks reduced arthritis compared to treatment with the aRW control and histologically, including a reduction of bone remodeling." (PMID 31552020, 2019). "After 7 weeks of treatment, longitudinal arthritis clinical scores indicated that only dual blockade of CSF1 and IL34 or TNFRII-Fc treatments were protective in CIA." (PMID 31552020, 2019). "In murine arthritis models, CSF1 appears to be the major driver of efficacy and macrophage differentiation in CIA or TNFΔARE." (PMID 31552020, 2019). "We report here that depending on the disease, single or dual blockade of IL34 and CSF1 is needed for controlling inflammation consistent with the concordant tissue-specific expression of both cytokines in diseases such as colitis or arthritis." (PMID 31552020, 2019). "As reported, the in vivo administration of CSF-1 exacerbated the inflammation and joint erosion in collagen-induced arthritis due to the role of CSF-1 in the pathology of osteoclastogenesis and subsequent osteolysis." (PMID 29326938, 2017). "Further, in experimental arthritis in mice injections of CSF-1 have been shown to exacerbate disease whereas CSF-1 blocking alleviates disease severity." (PMID 28779164, 2017). "Given that the expression of IL34 and CSF1 are both elevated in arthritis, and that CSF1R signaling is critical for macrophage differentiation and osteoclast homeostasis, we asked whether CSF1 and/or IL34 neutralization affected arthritis disease induction and outcome." (PMID 31552020, 2019). "However, it has also been shown that K/BxN serum-induced arthritis is independent of CSF-1-dependent macrophages since op/op mice, which lack CSF-1, were fully susceptible to arthritis." (PMID 27313578, 2016). "Animal models have shown that exogenous administration of CSF-1, like GM-CSF, exacerbates the incidence and severity of CIA, while anti-CSF-1 Ab, genetic deletion of CSF-1, and pharmacological inhibitors of CSF1R reduce the severity of experimental arthritis." (PMID 27036883, 2016). "CSF-1 or IL-34 stimulation of CSF1R promotes macrophage differentiation, activation and osteoclastogenesis, and pharmacological inhibition of CSF1R is beneficial in animal models of arthritis." (PMID 27036883, 2016).
glioblastoma (36 papers, 2011 to 2025). The most malignant astrocytic tumor (WHO grade IV). "Recent advances in immunotherapies have shown that addressing the tumor immune profile by targeting the colony‐stimulating factor 1 (CSF‐1) signaling pathway of tumor‐associated macrophages (TAMs) has the potential to improve glioblastoma therapy." (PMID 34027092, 2021). "For example, in the glioblastoma microenvironment, IL-6 and CSF-1, which are produced by glioblastoma-associated endothelial cells, increase arginase-1 expression, which is mediated by HIF-2α activation in monocyte-derived macrophages." (PMID 32655574, 2020). "The production of CSF-1 by glioblastoma cells attracts microglia and transforms them into a pro-tumorigenic phenotype, and microglia in turn stimulate glioblastoma cell invasion via EGFR activation." (PMID 37705736, 2023). "The in vitro upregulation of TREM1 in macrophages triggered the release of colony-stimulating factor-1 (CSF-1), triggering invasive activity and pathologic angiogenesis in glioblastoma cells." (PMID 35203505, 2022). "Tumour cells are identified as the source of CSF-1 in glioblastoma, and production can be enhanced following irradiation." (PMID 33803414, 2021). "Increased TAMs infiltration and a restored protumorigenic TME were observed as a result of radiotherapy induced activation of CCL2/CCR2 axis in pancreatic ductal adenocarcinoma and of the CSF-1/CSF-R axis in glioblastoma." (PMID 34988021, 2021). "As a result, in some glioblastoma models, inhibition of CSF1 led to a shift in TAM polarisation away from pro-tumourigenic phenotypes resulting in tumour regression independent of adaptive immunity." (PMID 32792542, 2020). "Anti-CSF1 immunotherapy, when used in combination with RT, prolonged survival in a glioblastoma (GBM) mouse model and significantly reduced RT-mediated macrophage recruitment to the tumor." (PMID 30766539, 2018). "The interaction between CSF‐1 and glial progenitor cells enhances the invasion of glioblastoma (GBM), while inhibition of CSF‐1R targeting glioma‐associated microglia may suppress GBM invasion." (PMID 40717900, 2025). "Moreover, the production of CSF1 by glioblastoma induces the release of the insulin-like growth factor-binding protein 1 (IGFBP1) by microglia which Is essential to promote vascularization and angiogenesis." (PMID 35311140, 2022). "CSF1 expression is significantly upregulated in glioblastoma compared to the normal brain." (PMID 33803414, 2021). "Glioblastomas induce them to adopt an activated phenotype; in cell culture, co-culture of glioblastoma cells with macrophages or microglia induces the latter to adopt an M2-like immunosuppressive phenotype, a process that is mediated by various cytokines including CSF-1, TGFβ, and GDF15." (PMID 33753869, 2022). "Colony-stimulating factor 1 (CSF-1) and chemokine (C-C motif) ligand 2 (CCL2), which are overexpressed in glioblastoma, attract macrophages and determine their behavior." (PMID 35406398, 2022). "Genes that show higher expression in astrocytoma compared to glioblastoma were CX3CL1, CSF1 (MCSF), CCL3 (MIP1α), CCL4 (MIP1β), TGFα, FLT3LG, CXCL5, CCL19 while KITLG (SCF) and NGF were equally expressed in the two tumor types." (PMID 35301393, 2022). "Though the CSF-1/CSF-1R pathway is required for TAM recruitment and survival, the inhibition of CSF-1R by BLZ945 was shown to repolarize TAMs in a glioblastoma multiforme mouse model." (PMID 34988021, 2021). "The number and function of TAMs are shaped by glioblastoma-derived soluble factors, such as the chemo-attractant CCL-2 and colony-stimulation factor 1 (CSF-1)." (PMID 32235752, 2020). "Additionally, BLZ945, a CSF-1 inhibitor, is tested as monotherapy and in combination with spartalizumab, a novel anti-PD1 monoclonal antibody, in solid cancers, including glioblastoma (NCT02829723)." (PMID 32235752, 2020).
osteopetrosis (35 papers, 2006 to 2024). Osteopetrosis, also known as marble bone disease, is a descriptive term that refers to a group of rare, heritable disorders of the skeleton characterized by increased bone density on radiographs. "CSF1 deletion was first implicated in bone when it was discovered that the cause of osteopetrosis in the op/op mouse model was due to a loss-of-function mutation in Csf1, resulting in drastically reduced numbers of macrophages and osteoclasts." (PMID 37688671, 2023). "The definitive phenotype of Csf1 and Csf1r mutations in mice and rats is osteoclast deficiency and osteopetrosis." (PMID 35333324, 2022). "By contrast, mutation of Csf1 in the toothless (tl/tl) rat is associated with unremitting osteopetrosis and OCL deficiency but a much less severe effect on postnatal somatic growth than in mice." (PMID 36197652, 2022). "Mice homozygous for the naturally occurring Csf1op (op: osteopetrosis) gene mutation lack Csf1, due to a spontaneous frameshift mutation, and have a reduced macrophage population in various organs." (PMID 31824413, 2019). "Although osteopetrosis is genetically diverse, mutations in CSF1 have been reported as autosomal recessive in humans." (PMID 31824413, 2019). "A natural mutation of the Csf1 gene in mice (op/op) produces a reduction in macrophage numbers in most tissues of the body, accompanied by severe growth retardation, osteopetrosis, and deficiencies in sensory, reproductive, and other endocrine systems." (PMID 24652541, 2014). "Mice and rats with a homozygous mutation in their CSF-1 gene are deficient in biologically active CSF-1 (op/op mice and tl/tl rats) and born with congenital osteopetrosis, reduced tissue macrophage populations and multiple developmental abnormalities." (PMID 22974529, 2012). "Similar to CSF-1 mutationCsf1op/Csf1op mice, deficiency of CSF1Ralso resulted in osteopetrosis, reduced mononuclear phagocyte and reproductivedefect indicating the function of CSF-1 is through CSF1R." (PMID 21494622, 2011). "Osteopetrosis (Csf1op/op) mice have a defect in the expression of macrophage colony stimulating factor (Csf1), which causes a severe deficiency of mature macrophages." (PMID 20625428, 2010). "There has been only one isolated report of recessive CSF1 mutation in human osteopetrosis." (PMID 36197652, 2022). "A loss of function mutation in the Csf-1 gene in mice produces the op/op model for osteopetrosis, which is accompanied by a number of overt manifestations such as a lack of teeth, stunted growth, a domed skull, and distinct reduction in the number of macrophages across several tissues." (PMID 32703234, 2020). "These investigators subsequently demonstrated that the osteopetrosis phenotype of CSF-1- and CSF1R-deficient mice could be replicated by post-natal administration of a neutralising anti-CSF-1 antibody." (PMID 21738673, 2011). "The requirement for M-CSF for osteoclastogenesis in vivo has been demonstrated with op/op mutant mice (op stands for osteopetrosis, a condition characterized by abnormally dense bone formation), where the M-CSF gene (Csf1) is inactivated." (PMID 38731934, 2024). "Focusing on the thin cortical bone and increased trabecular bone, which are common phenotype in osteopetrosis, here we take a classic osteopetrosis mouse model, Csf1−/− mice, as an example." (PMID 39419968, 2024). "Both groups found that deletion of CSF1 in MALPs drastically reduced whole-marrow CSF1 expression and led to osteopetrosis and reduced bone marrow macrophage abundance upwards of 50%." (PMID 37688671, 2023). "Partial correction of osteopetrosis was achieved by either co-expression of cell-surface M-CSF in the case of the Csf1op/Csf1op background, or cessation of neutralizing anti-CSF-1 antibody administration." (PMID 21738673, 2011).
osteopetrosis (continued). "The critical role of macrophage-colony stimulating factor (M-CSF) in osteoclast (OC) differentiation from hematopoietic precursors was demonstrated in mice with osteopetrosis due to disruption of the CSF-1 gene (Csf1op/Csf1op)." (PMID 21738673, 2011). "The definitive phenotype of the CSF1-deficient mouse is osteopetrosis, as a result of a complete lack of OCL." (PMID 24652541, 2014). "Mice lacking CSF1 exhibit severe osteopetrosis due to a decrease in osteoclastogenesis." (PMID 35336913, 2022). "Csf1op/op mice that express nonfunctional CSF1 lack osteoclasts and develop severe osteopetrosis." (PMID 33568650, 2021). "In addition to RANKL, M-CSF plays a critical role in osteoclast differentiation which was well-demonstrated in mice with severe osteopetrosis due to lack of CSF-1 gene (Csf 1°p/Csf 1°p)." (PMID 31555218, 2019).
osteoporosis (29 papers, 2011 to 2025). A condition of reduced bone mass, with decreased cortical thickness and a decrease in the number and size of the trabeculae of cancellous bone (but normal chemical composition), resulting in increased fracture incidence. "We developed the ovariectomy (OVX) model in Csf1∆Adipoq mice to study the contribution of Adipoq+ cell-produced M-CSF to the estrogen-deficiency induced osteoporosis, which mimics postmenopausal bone loss." (PMID 36779851, 2023). "CSF1 is crucial for the proliferation, differentiation, and motility of osteoclasts, making it a key therapeutic target for osteoporosis." (PMID 37853468, 2023). "There is some evidence for an effect of mouse genetic background on the penetrance of CSF1 mutations, and it is notable that C57BL/6J female develop early-onset osteoporosis." (PMID 36197652, 2022). "RANKL or CSF1 signalinghave been the target of clinical trials for the treatment of osteoporosis andautoimmune inflammatory diseases." (PMID 21494622, 2011). "The relative lack of effect of anti-CSF1 contrasts with the ability of anti-RANKL (Denosumab) to produce a 40–50% decline in TRAP5b at least in individuals with elevated TRAP5b associated with osteoporosis." (PMID 36197652, 2022). "Amid these, the colony-stimulating factor 1 (CSF-1) and the corresponding transmembrane receptor (CSF1R) play a significant role in the pathogenesis and progression of various diseases, including osteoporosis, cancer, and autoimmune disorders." (PMID 40573211, 2025). "It is observed that miR-195a suppressed both RANKL and CSF1 gene expression, which resulted in halted osteoclast formation and activity in OVX-induced osteoporosis." (PMID 39452495, 2024). "CSF1 treatment of adult mice produced a substantial increase in OCL numbers (unpublished results) and transgenic overexpression of CSF1 produces osteoporosis, indicating that OCL production/difference remains sensitive to availability of CSF1." (PMID 24652541, 2014). "For individuals with osteoporosis, preemptive genotyping for TREM2/DAP12, CSF1, CCR5, and Pyk2 signaling pathways could suggest relative risks for AD compared to population norm with a matched genetic background." (PMID 33568650, 2021). "Furthermore, CTSK, CSF1, TNFSF11, CTNNB1, TNFRSF11A, and TNF may be the most promising osteoporosis markers." (PMID 37893075, 2023).